MT-TL2 (mitochondrially encoded tRNA-Leu (CUN) 2)
Synonyms: TRNL2; formerly MTTL2
Gene: Mitochondrial transfer RNA gene on chromosome MT (12,266 to 12,336, forward strand). Ensembl gene ENSG00000210191.
Gene-disease validity (ClinGen):
ClinGen rates the evidence that MT-TL2 causes each of these diseases.
mitochondrial disease (mitochondrial): Definitive.
Leigh syndrome (mitochondrial): Disputed. A progressive neurological disease defined by specific neuropathological features associating brainstem and basal ganglia lesions.
Diseases named in the same sentence as MT-TL2 in open-access papers:
MT-TL2 is named in the same sentence as 7 diseases in open-access papers, as found by Europe PMC text mining. Sharing a sentence is not in itself a finding about the gene and the disease. The quoted sentences say what the papers report.
MELAS (2 papers, 2009 to 2014). "In support of this, we previously reported a novel MTTL2 gene mutation in a Saudi boy with typical clinical features of MELAS." (PMID 19946553, 2009). "Several other point mutations in the MT-TL2 gene have been implicated in mitochondrial diseases, including CPEO, MELAS (mitochondrial myopathy, encephalopathy, lactic acidosis, and stroke syndrome), and other mitochondrial myopathies including isolated dilated cardiomyopathy." (PMID 25223649, 2014).
MT-TL2 also shares sentences with these, for which no sentence is quoted: dilated cardiomyopathy (1 paper); Encephalopathy (1); lactic acidosis (1); mitochondrial disease (1); Mitochondrial myopathy (1); stroke syndrome (1).